MIR150 (microRNA 150)
Synonyms: hsa-mir-150; MIRN150; miRNA150; mir-150
Gene: MicroRNA gene on chromosome 19 (49,500,785 to 49,500,868, reverse strand). Ensembl gene ENSG00000207782.
Pathways (Reactome):
Signal Transduction: Pre-NOTCH Transcription and Translation
Gene Ontology:
Biological process: miRNA-mediated post-transcriptional gene silencing
Cellular component: RISC complex
Homologues: Orthologues: chimpanzee ptr-mir-150 (100% identical), rat Mir150 (93% identical), pig ssc-mir-150-1 (81% identical), mouse Mir150 (73% identical), guinea pig MIR150 (71% identical), dog MIR150 (61% identical), rabbit MIR150 (58% identical), tropical clawed frog xtr-mir-150 (52% identical), zebrafish mir150 (46% identical).
Diseases named in the same sentence as MIR150 in open-access papers:
MIR150 is named in the same sentence as 10 diseases in open-access papers, as found by Europe PMC text mining. Sharing a sentence is not in itself a finding about the gene and the disease. The quoted sentences say what the papers report.
autoimmune disease (1 paper, 2023). A disorder resulting from loss of function or tissue destruction of an organ or multiple organs, arising from humoral or cellular immune responses of the individual to their own tissue constituents. "Additionally, the altered expression of MIR-150 is a diagnostic biomarker of various autoimmune diseases." (PMID 37182123, 2023). "MIR-150 is upregulated or downregulated in many autoimmune diseases, such as multiple sclerosis (MS), myasthenia gravis (MG), systemic lupus erythematosus (SLE), rheumatoid arthritis (RA), and primary Sjogren’s syndrome (pSS)." (PMID 37182123, 2023).
chronic lymphocytic leukemia (1 paper, 2023). "The expression of MIR-150 in indolent primary cutaneous B-cell lymphoma and chronic lymphocytic leukemia is inversely related to patients’ survival time, helping the prognosis of the disease." (PMID 37182123, 2023). "MIR-150 is downregulated in several B-lymphocyte malignancies, such as diffuse large B-cell lymphoma (DLBCL), mantle cell lymphoma (MCL), BL and aggressive chronic lymphocytic leukemia (CLL)." (PMID 37182123, 2023).
Cirrhosis (1 paper, 2025). A chronic disorder of the liver in which liver tissue becomes scarred and is partially replaced by regenerative nodules and fibrotic tissue resulting in loss of liver function. "Notably, EID3, MIR150, and ZNF154 have been reported to exhibit differential expression between cirrhosis patients and HCC patients, suggesting their potential as biomarkers for early-stage HCC." (PMID 40500793, 2025).
mucositis (1 paper, 2022). Mucositis is inflammation and damage of the mucous membranes lining the mouth and other parts of the gastrointestinal (GI) tract. "MIR-150 deficiency reduced the intraepithelial lymphocyte population in the small intestine and increased susceptibility to anticancer drug-induced mucositis; hence, miR-150-mediated intraepithelial lymphocyte generation was crucial for maintaining intestinal integrity." (PMID 35739870, 2022).
cancer (2 papers, 2021 to 2024). A tumor composed of atypical neoplastic, often pleomorphic cells that invade other tissues. "Pan-cancer analysis showed that MIR129-2, MIR149, MIR152, MIR150, MIR34B, and MIR34C were downregulated in at least four types of cancer, and MIR150 had a protective role against death in most types of cancer." (PMID 33403044, 2021).
MIR150 also shares sentences with these, for which no sentence is quoted: diffuse large B-cell lymphoma (1 paper); mantle cell lymphoma (1); myasthenia gravis (1); rheumatoid arthritis (1); systemic lupus erythematosus (1).